NPY (neuropeptide Y)
Diseases named in the same sentence as NPY in open-access papers (continued):
Sharing a sentence is not in itself a finding about the gene and the disease.
schizophrenia (continued). "Moreover, there is sexual dimorphism of the NPY in schizophrenia." (PMID 39691787, 2024). "The NPY transcript isoform profile detected in this study is also consistent with reports that the expression of NPY (a member of the neuroactive ligand-receptor interaction pathway) was altered in the dorsolateral prefrontal cortex of individuals with schizophrenia." (PMID 33834688, 2021). "Notably, NPY in humans is found to be altered in schizophrenia, and bipolar disorder." (PMID 33192369, 2020). "Adult DEP9 males display lower NPY levels in the HPC than CTL rats, accompanied by impairment of PPI, suggesting a possible involvement of low NPY levels with schizophrenia-like behaviour." (PMID 37122626, 2023). "For example, modulators of NPY or SST signaling and drugs that increase the activity of the GABAergic pathway have been reviewed as attractive therapeutic opportunities for schizophrenia." (PMID 28809853, 2017). "It regulates BDNF, altering the expression of downstream GABAergic transcripts (NPY, SST and PV) in schizophrenia patients." (PMID 20156358, 2010). "Several studies have shown a clear relationship between reduced levels of neuropeptide Y (NPY) in the brain and the pathophysiology of schizophrenia." (PMID 19445674, 2009). "Multiple differentially expressed genes (KCNIP4, GRM3, PRKG1, NPY for inh-C, and TRPC3 for inh-CCK) were related to glutamate reception and calcium channel activity, indicating these processes are altered within inhibitory midbrain neurons in schizophrenia." (PMID 39397771, 2025). "For instance, there was a negative correlation between CSF NPY levels and social function in schizophrenia patients." (PMID 39691787, 2024). "Therefore, the objective of our study was to investigate relationships between the serum NPY levels and severity of psychiatric symptoms in schizophrenia patients, especially to explore the sexual heterogeneity, which would help explore what role NPY may play in schizophrenia." (PMID 39691787, 2024). "However, genetic data on PRLRH, PRLR, OXT, OXTR, and NPY in human T2DM and schizophrenia patients are scarce." (PMID 33315097, 2021). "Other candidate genes, PRL-releasing hormone receptor (PRLRH), PRL receptor (PRLR), oxytocin (OXT), oxytocin receptor (OXTR), and NPY, may also correlate with the PRL pathway and contribute to schizophrenia and T2DM." (PMID 33315097, 2021). "Among the investigated gene loci, the genes involved in the dopamine–prolactin pathway, including the neuropeptide Y gene (NYP) and prolactin gene (PRL), may also attract attention to their contribution to the comorbidity of schizophrenia and metabolic syndrome." (PMID 35806096, 2022).
Alzheimer disease (25 papers, 2014 to 2026). A progressive, neurodegenerative disease characterized by loss of function and death of nerve cells in several areas of the brain leading to loss of cognitive function such as memory and language. "For example, Alzheimer’s disease, characterized by progressive memory loss and cognitive decline, has been linked to dysregulation in neuropeptide systems, including NPY." (PMID 38425430, 2024). "NPY has been implicated in neurodegenerative diseases such as Alzheimer’s disease, Huntington’s disease, and Parkinson’s disease as a biomarker, neuroprotective factor, or potential therapeutic target." (PMID 34298907, 2021). "More recently, it has been shown that NPY was involved in Alzheimer's disease (AD) and NPY exerted neuroprotective action associated with changes in intracellular production of NGF." (PMID 33312521, 2020). "Recent studies revealed that many neuropeptides including ghrelin, neurotensin, pituitary adenylate cyclase-activating polypeptide (PACAP), neuropeptide Y, substance P, and orexin may be associated with the pathophysiology and potential therapy of Alzheimer's disease." (PMID 30687008, 2018). "We performed a systematic review of studies, for which we search using the keywords “Alzheimer’s disease and neuropeptide Y”, “Alzheimer’s disease and NPY”, “AD and NPY”, “Neuropeptide Y and Neurodegenerative disease”." (PMID 39585059, 2024). "Various studies have demonstrated a role of NPY and NPY Y1 receptors in emotional and learning deficits in Alzheimer’s disease models and their cholinergic recovery." (PMID 38020778, 2023). "For instance, in Alzheimer disease (AD), researchers observed decreased NPY levels and NPY receptors in patients’ brain (cerebral cortex and hippocampus), decreased NPY levels in cerebrospinal fluid (CSF), and decreased NPY levels in peripheral plasma." (PMID 35566093, 2022). "For example, apolipoprotein B (ApoB) is an effective BBB shuttle peptide, and the administration of ApoB-fused NPY successfully increased NPY activities in the brain of an Alzheimer’s disease mouse model, which reversed neurodegenerative pathology." (PMID 35203552, 2022). "Japanese scholars found in Osaka that the plasma NPY concentration of patients with Alzheimer's disease (AD) decreased, suggesting that NPY is involved in the pathogenesis of AD." (PMID 34422139, 2021). "The expression of neuropeptide Y changes under neurodegenerative diseases including Alzheimer's disease." (PMID 30687008, 2018). "In summary, the level of neuropeptide Y increases significantly in hippocampus of mouse Alzheimer's disease models." (PMID 30687008, 2018). "In this review article, we provide a description of recent advances of neuropeptides including ghrelin, neurotensin, PACAP, neuropeptide Y, substance P and orexin in Alzheimer's disease." (PMID 30687008, 2018). "Numerous studies have indicated that the neuropeptides including ghrelin, neurotensin, pituitary adenylate cyclase-activating polypeptide (PACAP), neuropeptide Y, substance P and orexin are closely related to the pathophysiology of Alzheimer's disease." (PMID 30687008, 2018). "An anomalous high expression level of neuropeptide Y with aging was detected in the hippocampal circuits of mouse model of Alzheimer's disease." (PMID 30687008, 2018). "While the singular administration of an NPY1R agonist or Ketamine did not produce significant results in our object-in-place task, the literature suggests that NPY and its agonists have the capacity to ameliorate spatial memory deficits in rodent models mimicking Alzheimer’s disease symptoms." (PMID 38667284, 2024). "Additionally, studies have shown a decrease in NPY-immunoreactive fibers within the dentate gyrus in Alzheimer’s disease models, indicating the potential of NPY1R agonists in modulating hippocampal functions." (PMID 38667284, 2024). "One study demonstrated that NPY regulated miR-30a in an in vitro model of Alzheimer's disease." (PMID 33390770, 2021).
Alzheimer disease (continued). "Accumulating evidence suggests that NPY may provide neuroprotection in neurodegenerative diseases, such as Alzheimer’s disease, Parkinson’s disease, Machado-Joseph’s disease, and Huntington’s disease." (PMID 34298907, 2021). "As in Alzheimer’s disease, NPY plays a vital role in both these diseases." (PMID 34344469, 2021). "A study has confirmed that NPY can regulate miR-30a in an in vitro model of Alzheimer’s disease." (PMID 31708788, 2019). "Neuropeptide Y has neuroprotective effects in Alzheimer's disease." (PMID 30687008, 2018). "Interestingly, NPY-ir cortical neurons are one of the first affected neuron populations in Alzheimer's disease, suggesting a unique vulnerability among interneurons that are known to be rather resistant to the disease." (PMID 24616688, 2014). "Furthermore, prolonged inhibition of ΔFosB using a ΔJunD construct to block ΔFosB signaling in a mouse model of Alzheimer’s disease, that exhibits spontaneous recurrent seizures, led to similar findings, with increased neuroinflammation and decreased NPY expression in mossy fibers." (PMID 38283700, 2023). "GSEA of NPY and SST revealed that Alzheimer’s disease, the cytokine–cytokine receptor interaction, and the notch signaling pathway showed an overall upregulation trend." (PMID 41009659, 2025). "Four hub genes, GFAP, NPY, SNAP25, and SST, were found as possibly hub aging-related genes in Alzheimer’s disease from machine algorithms by adopting the random forest, LASSO, SVM, and Boruta models." (PMID 41009659, 2025). "In addition to apoA-I, TTR is also involved on the cleavage of both neuropeptide Y (NPY) and Aβ peptide, suggesting an important role of TTR-mediated proteolysis either in physiologic or pathologic conditions, with major impacts on the biology of nervous system and Alzheimer's disease, respectively." (PMID 33362465, 2020).
metabolic syndrome (25 papers, 2009 to 2025). A cluster of metabolic risk factors for CARDIOVASCULAR DISEASES and TYPE 2 DIABETES MELLITUS. "Moreover, previous studies have demonstrated that dopamine agonist treatment can reduce hypothalamic NPY levels in the ob/ob leptin-deficient genetic model of metabolic syndrome." (PMID 34200262, 2021). "NPY has been linked to several disorders associated with metabolic syndrome." (PMID 23118773, 2012). "NPY-OEDβH mice have previously been shown to present with a metabolic syndrome -like phenotype, and fitting with this NPY-OEDβH mice gained more weight compared with WT mice in the current experiment." (PMID 31811615, 2020). "The metabolic phenotype of NPY-OEDβH mouse has been extensively characterized and includes adult-onset obesity, impaired glucose tolerance, and dyslipidemia." (PMID 31811615, 2020). "Prolonged activation of neuropeptide Y and its receptor system (NPY–NPY2R) in adipocytes and endothelial cells is associated to the increase of adipose tissue and metabolic syndrome." (PMID 30108549, 2018). "In an attempt to stimulate arteriogenesis through administration of a mediator without proinflammatory properties and the concurrent atherogenic side effects, Neuropeptide Y (NPY) was tested in swine suffering from metabolic syndrome." (PMID 23721076, 2014). "Our data suggested that NPY system mediates stress induced adipogenic commitment in embryo, and thus play an important role in prenatal stress programmed abdominal obesity and metabolic syndrome in offspring." (PMID 22570731, 2012). "For example, Kuo and colleagues report that stress dependent NPY release from sympathetic nerves promotes abdominal obesity and development of metabolic syndrome (including impaired glucose tolerance, hyperlipidaemia, hypertension, and increased concentrations of insulin, leptin and resistin)." (PMID 37153459, 2023). "Therefore, NPY is activated in adipose tissue, increasing lipogenesis and angiogenesis, leading to abdominal obesity and metabolic syndrome." (PMID 34344469, 2021). "Taken together, these findings suggest that an increased NPYergic tone leading to an enhanced NPY production may be an etiological factor in metabolic syndrome." (PMID 34445453, 2021). "CB1 receptors may offer a target for the pharmacological treatment of the metabolic syndrome with altered NPY levels." (PMID 25915740, 2015). "In addition, NPY is a stress-activated sympathetic cardiovascular and metabolic regulator that could influence co-morbidity patterns of stress-related disorders such as the metabolic syndrome." (PMID 34445453, 2021). "Nonetheless, in our study, intranasal administration of NPY did not affect body weight, food intake levels, white adipose tissue weight nor dyslipidemia parameters, such as cholesterol and triglycerides serum levels, of mice." (PMID 33558582, 2021). "HFD induced higher fasting glucose levels, serum HbA1c concentration and dyslipidemia while NPY overexpression did not induce any effects on blood glucose or lipids." (PMID 25993471, 2015).
atherosclerosis (23 papers, 2009 to 2025). A disease characterized by the build-up of fatty material and calcium deposition in the arterial wall resulting in partial or complete occlusion of the arterial lumen. "Although NPY is an important sympathetic neurotransmitter that has been implicated in restenosis and atherosclerosis, there are discrepancies in the literature and the underlying mechanisms are not fully understood." (PMID 37149580, 2023). "For example, genetic polymorphisms in the NPY gene and those of several of its receptors are associated with early‐onset atherosclerosis." (PMID 35766271, 2022). "Herein, we present an updated review of the possible mechanisms of nicotine-induced atherosclerosis, with a focus on endothelial cell dysfunction associated with nicotine and NPY." (PMID 33708805, 2021). "Different NPY single nucleotide polymorphisms have also been linked to higher plasma NPY levels and are reported to predict early onset atherosclerosis in US populations." (PMID 30283345, 2018). "In identifying the association between NPY variants and atherosclerosis, our results highlight the importance of pursuing a comprehensive gene-wide SNP survey." (PMID 19119412, 2009). "To assess a causal role of NPY in atherosclerosis, we applied the NPY1-receptor–antagonist BIBP-3226 adventitially to endothelium-denuded carotid arteries of apolipoprotein E-deficient mice; treatment reduced atherosclerotic neointimal area by 50% (p = 0.03)." (PMID 19119412, 2009). "Interestingly, both mutations in the ABC transporter and the minor allele of NPY (NPY-P) have been associated with atherosclerosis." (PMID 35627254, 2022). "NPY is associated with atherosclerosis, coronary heart disease, and pulmonary hypertension." (PMID 34344469, 2021). "In response to the results of the genome-wide linkage analyses, the phenotypic correlations, and the strong but limited prior published work, we proposed to test the hypothesis that NPY variants affect atherosclerosis through effects on NPY plasma levels." (PMID 19119412, 2009). "Thus, NPY variants associate with atherosclerosis in two independent datasets (with strong age-of-onset effects) and show allele-specific expression with NPY levels, while NPY receptor antagonism reduces atherosclerosis in mice." (PMID 19119412, 2009). "The link between NPY signaling and atherosclerotic complications is further strengthened by the identification of several single-nucleotide polymorphism in the NPY gene and a gain-of-function polymorphism associated with increased atherosclerosis in human patients." (PMID 31379881, 2019). "Out of 249 genes in significant modules that were not enriched in pathways or networks, four genes, LMNA and MMP12 at baseline, NPY and RXRA in females and males at 2y have previously been shown to be associated with atherosclerosis." (PMID 35925965, 2022). "Studies also found that the increase in NPY is accompanied by the activation of the G protein‐coupled Y‐family of receptors 1 and 5 (Y1R and Y5R) in atherosclerosis." (PMID 36172879, 2022). "Sympathetic activity affects atherosclerosis mainly via its transmitters for noradrenaline (NE), ATP and neuropeptide Y (NPY)." (PMID 36172879, 2022). "Neuropeptide Y (NPY), a neurotransmitter, is abundantly distributed in the peripheral nervous system and was shown to be increased in the artery wall and be related to atherosclerosis." (PMID 36172879, 2022). "Here, we investigated the effect of NPY on the changes in phenotype and functions of human macrophages, from the pro-inflammatory phenotype M1 to the reparative M2, indicative of atherosclerosis regression or stabilization." (PMID 36361795, 2022). "NPY participates in the pathogenesis of atherosclerosis by aggravating ED, VSMC growth, foam cell formation, and platelet aggregation, which are major pathogenic processes in cardiovascular disease." (PMID 34512386, 2021).
atherosclerosis (continued). "We have previously established, in experimental atherosclerosis models, that mast cells in the vessel wall can be activated via neuropeptides such as Substance P or Neuropeptide Y, or via complement components such as C5a." (PMID 30970663, 2019). "Neuropeptide Y activates cell proliferation in macrophages, megakaryocytes and VSMCs, and is reported to promote atherosclerosis, as well as contributing to hyperlipidemia." (PMID 26619277, 2015). "Our data provide the first evidence that NPY gene variants associate with CAD in humans, particularly those with early-onset CAD, and that NPY contributes to atherosclerosis in mice through its NPY1 receptor." (PMID 19119412, 2009). "We pursued a comprehensive gene-wide approach to correlating NPY variants with CAD and plasma NPY levels in humans, and tested the effects of NPY1 receptor blockade on atherosclerosis in mice." (PMID 19119412, 2009). "Gene expression analysis reveals that polymicrobial infection alters 6 of 84 atherosclerosis-related genes by more than 3-fold, including upregulation of neuropeptide Y (promoting atherosclerosis) and downregulation of apolipoprotein genes crucial for lipid transport." (PMID 40869031, 2025). "This study provides a better understanding of neointima formation and highlights the potential that blocking NPY signaling may have beneficial effects in atherosclerosis and restenosis." (PMID 37149580, 2023). "The role of NPY in the onset and course of atherosclerosis is still largely debated." (PMID 36361795, 2022). "Since foam formation in the artery wall is inseparable from the role of macrophages and NPY not only enhances the process of atherosclerosis but also influences the function of macrophages, the relationships of NPY, macrophages and atherosclerotic plaques attracted our attention." (PMID 36172879, 2022). "In several animal and in vitro studies, it has been shown that NPY exerts pro-atherogenic actions during stress, vascular injury, and ischemia, even though contradictory results exist on the role played by the NPY-Y1R axis on atherosclerosis progression." (PMID 36361795, 2022). "Abnormal regulation of NPY is involved in the development of atherosclerosis." (PMID 36361795, 2022). "Also, there are other ways in which NPY plays an important mechanistic role in the pathophysiology of atherosclerosis, STEMI, and ischemic heart failure." (PMID 35766271, 2022). "Whether NPY-mediated endothelial function forms a positive feedback loop after sympathetic excitation and ultimately leads to the deterioration of atherosclerosis remains to be clarified." (PMID 34512386, 2021). "NPY can increase the levels of calcium in the cytoplasm of vascular smooth muscle cells, activate protein kinase C and promote mitosis, thereby leading to atherosclerosis." (PMID 34307371, 2021). "NPY may be involved in the pathogenesis of atherosclerosis, in addition to maintaining cardiac contraction, promoting ventricular hypertrophy, and reducing parasympathetic nerve activity." (PMID 30859228, 2019). "We conclude that NPY contributes to atherosclerosis pathogenesis." (PMID 19119412, 2009). "NPY signaling may have a crucial role in tissue homeostasis in host inflammatory responses through the regulation of macrophage balance and functions within atherosclerosis." (PMID 36361795, 2022). "To determine whether NPY-evoked signaling contributes to atherosclerosis, we attenuated the vascular effects of NPY with an NPY1 receptor antagonist that does not cross the blood-brain barrier: BIBP 3226 (BIBP), which has been shown to reduce non-atherosclerotic neointimal hyperplasia in rats." (PMID 19119412, 2009). "The possibility that NPY contributes to atherosclerosis is supported by the correlation of plasma NPY levels with NPY SNP risk alleles, and the inhibition of murine atherosclerosis with an antagonist of the NPY1 receptor, which mediates most cardiovascular effects of NPY." (PMID 19119412, 2009).
atherosclerosis (continued). "Therefore, NPYR present in macrophages appears to be an important pathway by which NPY stimulates macrophage chemotaxis, implying that the antagonism of excessive NPYR activation could be a potential therapeutic target for the complications associated with atherosclerosis." (PMID 31379881, 2019).